YTHDC2 (YTH N6-methyladenosine RNA binding protein C2)
Diseases named in the same sentence as YTHDC2 in open-access papers (continued):
Sharing a sentence is not in itself a finding about the gene and the disease.
esophageal squamous cell carcinoma (6 papers, 2021 to 2024). Esophageal squamous cell carcinoma (ESCC) is a type of esophageal carcinoma (EC) that can affect any part of the esophagus, but is usually located in the upper or middle third. "Another study suggested that the YTHDC2 rs2416282 variant contributed to esophageal squamous-cell carcinoma risk by regulating YTHDC2 expression." (PMID 36072379, 2022). "Additionally, genetic variations within the YTHDC2 promoter, such as the single nucleotide polymorphism (SNP) rs2416282, influence YTHDC2 expression and are associated with esophageal squamous cell carcinoma risk." (PMID 38790013, 2024).
cervical cancer (5 papers, 2021 to 2022). A primary or metastatic malignant neoplasm involving the cervix. "YTHDC2 which plays a significant role in epigenetic modification and immune infiltration could cause a different prognosis in cervical cancer." (PMID 36072430, 2022). "Through further GO and KEGG clustering analysis of the functions of these three factors (YTHDC1, YTHDC2 and RBM15), we infer that ERBB3 methylation plays an important role in the occurrence and progression of cervical cancer." (PMID 35581263, 2022). "Differential analysis results showed that many m6A-related genes were differentially expressed between cervical cancer tissues and normal tissues, including METTL14, METTL16, ZC3H13, YTHDC1, and YTHDC2." (PMID 36058934, 2022).
gastric cancer (5 papers, 2019 to 2024). A primary or metastatic malignant neoplasm involving the stomach. "Several studies have reported that YTHDC2 expression is linked to unfavorable prognosis in colorectal, breast, and gastric cancers, which is congruent with the findings of the current study." (PMID 38787520, 2024). "For instance, elevated levels of YTHDF1 and YTHDC2 are adverse prognostic factors for gastric cancer (GC), while increased IGF2BP3 levels are adverse prognostic factors for bladder cancer." (PMID 39062595, 2024). "YTHDC2 facilitates the proliferation, migration, and invasion of gastric cancer (GC) cells both in vivo and in vitro." (PMID 38790013, 2024). "The results indicated that high expression of FTO (HR = 1.15, 95% CI = 1.02–1.29), HNRNPC (HR = 1.09, 95% CI = 1.02–1.18), YTHDC2 (HR = 1.22, 95% CI = 1.07–1.42), and WTAP (HR = 1.18, 95% CI = 1.02–1.33) have a worse survival in patients with gastric cancer." (PMID 31681576, 2019).
liver cancer (5 papers, 2020 to 2025). An epithelial or non-epithelial malignant neoplasm that arises from the liver. "Whereas opposite evidence of YTHDC2 as a tumor suppressor gene is also reported in liver cancer, covering the underneath mechanisms a heterogeneous veil." (PMID 34497675, 2021). "However, the role of YTHDC2 in liver cancer immunotherapy still requires more in-depth research to clarify its specific mechanisms and clinical significance." (PMID 39911396, 2025). "Future exploration of YTHDC2 may provide new insights and targets for liver cancer immunotherapy, offering new opportunities to improve treatment outcomes and prognosis for patients." (PMID 39911396, 2025). "Some studies suggest that YTHDC2 might work synergistically with other immune-regulatory factors to co-regulate the liver cancer cells’ response to the immune system." (PMID 39911396, 2025). "Inhibiting WTAP or YTHDC2 effectively suppresses ferroptosis and liver cancer progression." (PMID 39135292, 2024). "Studies indicate that YTHDC2 might interact with m6A-modified mRNA, influencing the expression and regulation of related genes, thereby indirectly participating in the modulation of liver cancer immune responses." (PMID 39911396, 2025). "Unlike the low expression of YTHDC2 in LUAD, YTHDC2 expression was increased in liver cancer and positively related to tumor malignancy." (PMID 34497675, 2021).
Insulin resistance (4 papers, 2021 to 2024). Increased resistance towards insulin, that is, diminished effectiveness of insulin in reducing blood glucose levels. "Overexpression of YTHDC2 in the livers of obese mice improved hepatic lipid metabolism and insulin resistance." (PMID 35057432, 2022). "YTHDC2 was found to be markedly down-regulated in obese mice and its overexpression improved the liver steatosis and insulin resistance through binding to the mRNA of lipogenic genes." (PMID 34503454, 2021). "Similarly, YTHDC2 has been shown to suppress hepatic lipogenesis and TG homeostasis, making it a potential target for treating liver steatosis and insulin resistance." (PMID 38196046, 2024). "Inhibiting the expression of YTHDC2 in the liver of normal mice resulted in the deposition of TG; while overexpression of the YTHDC2 gene in the liver of obese mice improved liver lipid deposition and insulin resistance." (PMID 34950107, 2021).
lymph node metastasis (4 papers, 2021 to 2024). "In non-small cell lung cancer, a research analyzed a series of publicly available online databases and found that low YTHDC2 expression was associated with lymph node metastasis and poor prognosis." (PMID 34178026, 2021). "Notably, bioinformatics and tissue arrays analysis demonstrated that decreased YTHDC2 was highly associated with smoking history, pathological stage, invasion depth, lymph node metastasis and poor outcomes." (PMID 34326699, 2021). "In PC, YTHDC2 was significantly upregulated, positively correlating with Gleason grading and being notably higher in lymph node metastasis castration-resistant prostate cancer (CRPC) compared to CRPC with bone metastasis." (PMID 38790013, 2024). "METTL3, YTHDC2, YTHDF1, and YTHDF2 had a remarkably high expression in PCa and CRPC with lymph node metastasis." (PMID 33403026, 2021). "The expression of METTL3, METTL14, WTAP, YTHDC2, YTHDF1, and YTHDF2 was remarkably higher in CRPC with lymph node metastasis than in CRPC with bone metastasis, whereas ALKBH5, FTO, and YTHDF3 were substantially decreased in CRPC with lymph node metastasis." (PMID 33403026, 2021).
melanoma (4 papers, 2020 to 2024). A malignant, usually aggressive tumor composed of atypical, neoplastic melanocytes. "In GEO datasets, except YTHDC2, other m6A readers like YTHDF1, YTHDF2, YTHDF3 and YTHDC1 have a significant higher expression in melanoma tissues." (PMID 36324258, 2022).
skin cutaneous melanoma (4 papers, 2021 to 2023). "Moreover, YTHDC2 had a high diagnostic value for seven cancer types and a prognostic value for brain lower grade glioma (LGG), rectum adenocarcinoma (READ) and skin cutaneous melanoma (SKCM)." (PMID 34312987, 2021). "In addition, WTAP, YTHDC1 and YTHDC2 are widely positively correlated with anti-tumor immune-related genes, while IGF2BP3 is widely negatively correlated with these genes, which may be involved in the immune escape of skin melanoma cells." (PMID 34737950, 2021).
thyroid cancer (4 papers, 2021 to 2024). "YTHDC2 downregulated and exerted anti-cancer effects in both thyroid cancer tissues and cell lines." (PMID 38790013, 2024).
asthma (3 papers, 2021 to 2024). "Moreover, another study on childhood asthma found that m6A regulators also played a crucial role and screened five candidate m6A regulators (FMR1, KIAA1429, WTAP, YTHDC2, and ZC3H13) to predict the risk of childhood asthma." (PMID 35712670, 2022). "An RF model was established to select five candidate m6A regulators (FMR1, KIAA1429, WTAP, YTHDC2, and ZC3H13) from the 21 m6A regulators to predict the occurrence of childhood asthma." (PMID 33763115, 2021).
non-small cell lung carcinoma (3 papers, 2021 to 2024). A group of at least three distinct histological types of lung cancer, including non-small cell squamous cell carcinoma, adenocarcinoma, and large cell carcinoma. "In non-small cell lung cancer, down-regulation of the m6A reader YTHDC2 promotes tumor progression and predicts poor prognosis." (PMID 33748145, 2021). "We then reviewed the proteomic data and found YTHDC2 protein was reported significantly underexpressed in non-small cell lung cancer." (PMID 34178026, 2021). "Additionally, YTHDC2 inhibited drug resistance in non-small cell lung cancer (NSCLC) by upregulating the expression of the tumor suppressor gene Inhibitor of DNA-binding 3 (ID3) in cisplatin-resistant NSCLC cell lines." (PMID 38790013, 2024).
sarcoma (3 papers, 2021 to 2022). A usually aggressive malignant neoplasm of the soft tissue or bone. "Yet, YTHDC2 was positively associated with tumour purity in 10 cancer types, such as BRCA, SKCM, SKCM‐primary, glioblastoma multiforme (GBM), BRCA‐Luminal, BLCA, Sarcoma (SARC), TGCT, LGG and ACC." (PMID 34312987, 2021).
type 2 diabetes (3 papers, 2021 to 2023). "In addition, the whole exome sequencing has identified a variant of YTHDC2 which may contribute to type 2 diabetes susceptibility in Northeast India." (PMID 34503454, 2021). "In vascular smooth muscle cell (VSMC) dysfunction mediated by type 2 diabetes conditions, studies have shown that metformin restores TET2 by inhibiting the expression of YTHDC2 and circYTHDC2, thereby preventing the progression of VSMC dysfunction under high glucose conditions." (PMID 38012545, 2023).
virus infection (3 papers, 2024 to 2025). "Therefore, it is evident that ELAVL1 and YTHDC2 genes may be associated with the m6A methylation process in MDD through virus infection pathways." (PMID 38714976, 2024). "ISG20 is activated by IFN-β early in viral infection, while YTHDC2 recruits ISG20 to degrade IFN-β mRNA later in the disease progression." (PMID 40066451, 2025). "In addition, the Ythdc2-170aa polypeptide cannot be detected under normal conditions, but we found that the Ythdc2-170aa polypeptide was generated in large quantities under the condition of SCRV virus infection." (PMID 38361078, 2024).
bladder cancer (2 papers, 2022 to 2025). "In this study, we uncovered that the depletion of YTHDC2 significantly increased the pool of bladder cancer stem cells (BCSCs), resulting in a phenotypic shift towards a more invasive subtype of bladder cancer." (PMID 41145440, 2025). "To verify the biological function of YTHDC2 in bladder cancer, we firstly detected the endogenous YTHDC2 level in 5637, T24, UM-UC-3, J82." (PMID 41145440, 2025). "Collectively, these findings suggest that YTHDC2 potentially functions as a tumor suppressor in bladder cancer, where its downregulation correlates with aggressive clinicopathological features." (PMID 41145440, 2025). "Mechanistically, YTHDC2 inhibits bladder cancer progression by binding to m6A-modified SOX2 mRNA and suppressing SOX2 protein translation." (PMID 41145440, 2025). "In our study, YTHDC2 modulated SOX2 at translational level in bladder cancer cells, consistent with the established mechanism observed for this m6A reader across multiple cancer types." (PMID 41145440, 2025). "Patients with different subtypes and stages of bladder cancer consistently showed better prognosis when there is higher YTHDC2 expression in tumor." (PMID 41145440, 2025). "To uncover how YTHDC2 suppresses bladder cancer, we conducted RNA sequencing, proteomics, and m6A methylated RNA immunoprecipitation (MeRIP) sequencing to identify the potential downstream effectors." (PMID 41145440, 2025). "Among these 9 potential targets, SOX2-clinically correlated with poor prognosis and aggressive BCa subtypes -emerged as a key potential mediator of YTHDC2’s function in bladder cancer." (PMID 41145440, 2025). "Specifically, we found that YTHDC2 can regulate the characteristics of bladder cancer stem cells by recognizing m6A-modified SOX2." (PMID 41145440, 2025). "In this study, we identified YTHDC2 as a tumor suppressor in bladder cancer." (PMID 41145440, 2025). "Collectively, these results supported that YTHDC2 acts as a tumor suppressor in bladder cancer." (PMID 41145440, 2025). "We next explored the potential biological functions of YTHDC2 in bladder cancer." (PMID 41145440, 2025). "Furthermore, results of flow cytometry demonstrated that YTHDC2 knockout increased the ALDH1+ cells and CD133+ populations (markers for bladder cancer stem cells) in 5637-derived tumorspheres, while in T24, overexpression of YTHDC2 decreased the ratio of CD133+ subpopulation." (PMID 41145440, 2025). "In the present study, we identified the m6A reader YTHDC2 as a tumor suppressor by inhibiting proliferation, EMT and stemness in bladder cancer." (PMID 41145440, 2025).
breast tumor (2 papers, 2022 to 2025). "We examined YTHDC2 expression levels by immunohistochemistry in human breast tumor tissues from 99 patients and found a significantly positive correlation between the YTHDC2 expression level and the tumor stage." (PMID 36245989, 2022). "The YTHDC2 expression levels were positively correlated with the breast tumor stages (Spearman r = 0.216; P = 0.032)." (PMID 36245989, 2022).
childhood asthma (2 papers, 2021). "Moreover, in another study on childhood asthma found that m6A regulators also played a crucial role, and screened five candidate m6A regulators (FMR1, KIAA1429, WTAP, YTHDC2 and ZC3H13) to predict the risk of childhood asthma." (PMID 34647423, 2021).
clear cell renal cell carcinoma (2 papers, 2022 to 2024). "Compared with normal kidney tissue, the expression of m6A CNV amplification regulator YTHDC2 in clear cell renal cell carcinoma tissue was significantly increased (p < 0.05)." (PMID 35281520, 2022).
diffuse large B-cell lymphoma (2 papers, 2021). "The expression level of YTHDC2 was significantly upregulated in CHOL, lymphoid neoplasm diffuse large B‐cell lymphoma (DLBC), kidney renal clear cell carcinoma (KIRC), acute myeloid leukaemia (LAML), LGG, pancreatic adenocarcinoma (PAAD) and thymoma (THYM)." (PMID 34312987, 2021).
epilepsy (2 papers, 2022 to 2024). A brain disorder characterized by episodes of abnormally increased neuronal discharge resulting in transient episodes of sensory or motor neurological dysfunction, or psychic dysfunction. "To explore the effect of YTHDC2 knockdown on epileptic seizures, we injected an AAV carrying the GFAP promoter and eGFP into the bilateral hippocampus of mice with epilepsy to specifically reduce YTHDC2 expression in astrocytes." (PMID 39310099, 2024). "We found a consistent and dramatic increase in YTHDC2 at different time points after epilepsy induction." (PMID 39310099, 2024). "To exclude the potential influence of pilocarpine on YTHDC2 and m6A methylation, we conducted in vitro experiments using kainic acid (KA)—another common epilepsy modeling drug." (PMID 39310099, 2024). "In the epilepsy mouse model, YTHDC2 knockdown also effectively controlled seizures, suggesting YTHDC2 as a potential target for epilepsy therapy." (PMID 39310099, 2024). "The random forest (RF) model was applied to the screening, and seven m6A regulators (HNRNPC, WATP, RBM15, YTHDC1, YTHDC2, CBLL1, and RBMX) were selected as the candidate genes for predicting the risk of epilepsy." (PMID 36468034, 2022). "Through a series of in vivo and in vitro experiments, we provide evidence that targeting xCT and YTHDC2 in reactive astrocytes significantly reduces extracellular glutamate and mitigates seizure activity, offering novel therapeutic targets for epilepsy treatment." (PMID 39310099, 2024). "Additionally, the number of astrocytes colocalized with YTHDC2 showed a marked increase in mice with epilepsy." (PMID 39310099, 2024). "Hence, the increase in YTHDC2 was consistent across different epilepsy models." (PMID 39310099, 2024). "Firstly, we analyzed the expression of 17 m6A-related genes extracted from a public dataset and found that seven of them (HNRNPC, WTAP, RBM15, YTHDC1, YTHDC2, CBLL1, and RBMX) were differentially expressed between patients with epilepsy and healthy individuals." (PMID 36468034, 2022).
glioblastoma (2 papers, 2020 to 2021). The most malignant astrocytic tumor (WHO grade IV). "We used the TCGA microarray database and compared the mRNA expression levels of five YTH domain family proteins, YTHDF1, YTHDF2, YTHDF3, YTHDC1, and YTHDC2, between 720 normal brain tissue microarray datasets and 582 glioblastoma datasets." (PMID 33317545, 2020).
male infertility (2 papers, 2023 to 2024). The inability of the male to effect fertilization of an ovum after a specified period of unprotected intercourse. "Mutant mice with loss of YTH domain containing 2 (Ythdc2) also show male infertility through alterations in gene expression involved in the transition from mitosis to meiosis and telomere clustering in pachytene cells." (PMID 37146971, 2023). "Conditional deletion of m6A "reader" proteins, Ythdf2, Ythdc1, and Ythdc2, in mouse germ cells has resulted in aberrant regulation of post-transcriptional m6A modification on mRNAs, leading to male infertility." (PMID 38363375, 2024).
ovarian carcinoma (2 papers, 2021). A malignant neoplasm originating from the surface ovarian epithelium. "Two GEO databases demonstrated that 7 readers (HNRNPC, IGF2BP1, IGF2BP2, IGF2BP3, RBMX, YTHDC2, and YTHDF2) and 3 writers (METTL3, RBM15, and RBM15B) were more highly expressed in ovarian cancer than in ovarian surface epithelium or normal peritoneum tissues (GEO14407 and GEO12470)." (PMID 33225598, 2021). "HNRNPC, YTHDC2 and ZC3H13 genes were depleted in ovarian cancer." (PMID 34149801, 2021).
ovarian insufficiency (2 papers, 2022 to 2024). "One study showed that YTHDC2 expression was higher in late-stage ovaries, and that the disruption of YTHDC2 expression in mice led to impaired meiosis and an ovarian insufficiency phenotype." (PMID 38377031, 2024).
prostate carcinoma (2 papers, 2020 to 2023). A carcinoma that arises from epithelial cells of the prostate gland. "YTHDC2 is enriched in pathways of ubiquitin-mediated proteolysis, long-term potentiation, and prostate cancer." (PMID 32596399, 2020). "In addition, the expression levels of METTL3, FTO (Zhu, Li & Xu, 2021), YTHDF1-2, YTHDC2 were positively correlated with the Gleason score of prostate cancer." (PMID 37701836, 2023). "In prostate cancer, m6A modification level was upregulated, and the expression levels of METTL3, METTL14, VIRMA, RNA binding motif protein 15 (RBM15), HNRNPC, HNRNPA2B1, YTHDC2, YTHDF1 and YTHDF2 increased." (PMID 37701836, 2023).
steatosis (2 papers, 2021 to 2022). Increased lipid within the cytoplasm of cells. "RBM15, YTHDC2, HNRNPC, HNRNPA2B1, and EIF3H were related to steatosis." (PMID 36120320, 2022). "A study pointed out that YTHDC2 was markedly downregulated in the livers of obese mice and NAFLD patients and its overexpression in the livers of obese mice improved liver steatosis, which was consistent with our results that YTHDC2 expression decreased in NAFLD and was related to steatosis." (PMID 36120320, 2022).
adrenocortical carcinoma (1 paper, 2023). "YTHDC2 plays a role in the different methylation levels observed in uterine corpus endometrioid carcinoma, adrenocortical carcinoma (ACC), and endocervical adenocarcinoma (CESC), leading to different prognoses and levels of immune cell infiltration." (PMID 37964279, 2023).
Anxiety (1 paper, 2024). Intense feelings of nervousness, tension, or panic often arise in response to interpersonal stresses. "Among all the m6A genes, ELAVL1 and YTHDC2 are closely associated with MDD, ELAVL1 is related to comorbid anxiety in MDD." (PMID 38714976, 2024).
atherosclerosis (1 paper, 2025). A disease characterized by the build-up of fatty material and calcium deposition in the arterial wall resulting in partial or complete occlusion of the arterial lumen. "The m6A modification mediated by YTHDC2 stabilizes circYTHDC2, highlighting the potential of the YTHDC2/circYTHDC2/TET2 pathway as an important target to inhibit atherosclerosis through dedifferentiation methods." (PMID 40005339, 2025).